CYMP-AS1 (CYMP antisense RNA 1)
Gene: Long non-coding RNA gene on chromosome 1 (110,487,680 to 110,490,281, reverse strand). Ensembl gene ENSG00000235407.
Diseases named in the same sentence as CYMP-AS1 in open-access papers:
CYMP-AS1 is named in the same sentence as 1 disease in open-access papers, as found by Europe PMC text mining. Sharing a sentence is not in itself a finding about the gene and the disease. The quoted sentences say what the papers report.
tumor (1 paper, 2025). "CYMP-AS1 knockdown remarkably decreased the tumor tissue volume and weight versus the control group." (PMID 40746892, 2025).